CRP (C-reactive protein)
Diseases named in the same sentence as CRP in open-access papers (continued):
Sharing a sentence is not in itself a finding about the gene and the disease.
liver disease (continued). "Systemic inflammatory markers such as C-reactive protein (CRP), lipopolysaccharide (LPS), interleukin-6 (IL-6), tumor necrosis factor-alpha (TNF-α), soluble CD14 (sCD14), soluble CD163 (sCD163), and D-dimer are linked to cardiovascular and liver diseases." (PMID 39529759, 2024). "Furthermore, the positive correlation between BMG, BDG, and inflammatory markers such as CRP and leukocytes further solidifies the role of these bilirubin species as indicators of systemic inflammation in liver disease." (PMID 39125751, 2024). "CRP levels may be influenced by age, gender, weight, blood pressure, liver diseases, medications, and genetic preconditions." (PMID 37176498, 2023). "However, in patients with severe cirrhosis, the increase in CRP is often reduced, pointing to a defective acute phase reaction in advanced liver disease and limiting the prognostic value of CRP in the intensive care setting." (PMID 37048641, 2023). "CRP > 30 mg/dL and serum lactate > 18 mg/dL were assigned the highest score of 4 points; serum creatinine ≥ 1.6 mg/dL and comorbid liver disease were assigned the score of 3 points; and WBC count > 15 × 104/uL, hemoglobin < 11 g/dL, and blood glucose ≥ 180 mg/dL were assigned the score of 2 points." (PMID 34039397, 2021). "CRP is an acute phase reactant, which increases in infectious diseases and non-infectious inflammatory disorders, such as rheumatoid arthritis, systemic lupus erythematous, kidney or liver diseases." (PMID 34856956, 2021). "In the overall cohort, CRP was significantly higher in the patients with high-risk (HVPG ≥ 20 mmHg) versus non-high-risk (HVPG 6-19 mmHg) portal hypertension, but all other parameters were not significantly different." (PMID 33000389, 2020). "Furthermore, CRP is produced in the liver, and its production is significantly impaired in patients with liver disease or after hepatectomy as shown in this present study." (PMID 26880899, 2016). "This difference in the kinetics of WBC and CRP is explainable, as CRP shows an individual stability and narrow normal range, is barely influenced by common comorbidities (except liver diseases), and shows distinctive patterns with different surgical approaches." (PMID 25585544, 2015). "C-reactive protein (CRP)-to-albumin ratio (CAR), NAR, and NLR have been reported to be associated with poor liver function in patients with liver cirrhosis, and nutritional and inflammation-based indices may play a role in liver function in liver disease." (PMID 40747208, 2025). "Similarly, the CRP/albumin ratio has been recognized as a composite marker that captures both the inflammatory state and nutritional status, two key prognostic domains in advanced liver disease." (PMID 41590616, 2025). "High levels of CRP may be an alarming factor in the progression of liver disease." (PMID 37763758, 2023). "However, CRP is a poor indicator of inflammation in advanced liver disease since its production may be hampered by the liver dysfunction." (PMID 34504150, 2021). "Notably, the survival analysis based on our dataset showed that the reduced survival rate in patients with liver diseases was associated with the increased D‐dimer, but not the elevated CRP." (PMID 33112011, 2021). "As expected, patients with decompensated cirrhosis had more advanced liver disease with higher levels of Child–Pugh stage, MELD score, and signs of systemic inflammation including white blood cell count (WBC) and CRP levels." (PMID 40317887, 2025). "Alongside ferritin, other inflammatory biomarkers such as C-reactive protein (CRP) and interleukins—particularly IL-6—are elevated in liver disease and post-transplantation states." (PMID 40765572, 2025). "C-reactive protein (CRP), an acute-phase inflammatory marker produced in the liver, manifests elevated levels in advanced liver disease and correlates with increased mortality from systemic inflammation." (PMID 39685802, 2024).
liver disease (continued). "SLD, steatotic liver disease; ICU, intensive care unit; CT, computed tomography; CRP, C-reactive protein; AST, aspartate aminotransferase; ALT, alanine aminotransferase; ALP, alkaline phosphatase; GGT, gamma-glutamyltransferase." (PMID 38731216, 2024). "Criteria of exclusion: past or present cancer (treated with chemo-/radiotherapy), diseases of the liver (ALT > 3 × ULN) except for people with simple hepatic steatosis, chronic renal disease (eGFR < 30 mL/1.73 m2/min), and acute inflammation (CRP > 5 mg/dL)." (PMID 33668851, 2021). "The significance of serum CysC, serum Hcy, serum CRP, CAR, ALBI score, FIB-4 index, APRI, GPR, and GAR in the diagnosis and prognosis of HBV-related liver diseases has been indicated in many studies." (PMID 32774512, 2020). "Western blotting validated that CRP was dramatically higher in the serum of AFL compared to healthy controls and other animals with liver disease of NAFL or liver fibrosis (p < 0.05)." (PMID 21806828, 2011). "In this study, we discovered that CRP levels were elevated in AFL rats compared to healthy animals, and rats with other forms of liver diseases, such as NAFL and TAA-induced liver fibrosis." (PMID 21806828, 2011). "For CRP, significant differences were observed in Child-Pugh classification (p = 0.0023) and the presence of PVTT (p = 0.0022), with higher CRP levels in patients with more advanced liver disease and PVTT." (PMID 41458972, 2025). "These included a history of peptic ulcer, liver disease, an endoscopic finding of esophageal varices, as well as heart rate, systolic blood pressure, hemoglobin levels, GBS score, AIMS65 score, platelet count, and CRP levels." (PMID 41585275, 2025). "Furthermore, in line with previous research25we detected an increase in c-reactive protein (CRP) levels with progression of liver disease, underscoring the link between systemic inflammation and liver disease severity." (PMID 41028194, 2025). "The utilized serum markers of the disease (CRP) are characterized by a lack of specificity or false negative results in some forms of the disease (only limited to the small intestine) and in liver diseases." (PMID 39796508, 2024). "However, the relative change in IgG (Δ-IgG) independently predicted OS in multivariable Cox regression analysis after adjusting for severity of liver disease, baseline AFP and CRP as well as for Δ-IgA and Δ-IgM." (PMID 37027398, 2023). "Moreover, cytokine storm, also known as cytokine release syndrome (CRS), identified CRP, IL-6, LDH, and ferritin promotion, leading to ARDS and liver disorders." (PMID 36531832, 2022). "In the subgroup of liver diseases, patients with elevated LDH and D‐dimer had a lower survival rate compared with the controls; however, no significant change in survival rate was observed in patients with elevated CRP or reduced lymphocytes." (PMID 33112011, 2021). "CRP may be used as a marker for early detection and monitoring of SBP in children with liver disease with high sensitivity and specificity." (PMID 30289914, 2018). "From our rodent models, we determined that CRP levels were significantly elevated in the serum of rats with AFL, presumably as a reliable biomarker compared to that in livers of healthy or sick rats with other liver diseases." (PMID 21806828, 2011). "Importantly, they persist despite repeated negative evaluations for C-reactive protein (CRP) and erythrocyte sedimentation rate (ESR), homeostatic iron regulator (HFE) gene mutations, or hepatic disease." (PMID 41256943, 2025). "In addition to ESR, CRP, and BMG, it is important to note that LD activity is also a nonspecific marker and can be elevated in many other conditions, such as other types of cancer, hemolysis, liver disease, and infections." (PMID 39435165, 2024).
liver disease (continued). "Of these, 122 were excluded (reasons not mutually exclusive) due to recent iron therapy (<3 months), not meeting the inclusion criteria for IDA, CRP ≥ 10.0 mg/L, active inflammatory conditions, malignancy, bariatric surgery, severe kidney or liver disease, or no written informed consent." (PMID 35163840, 2022). "Moreover, increases in CRP are paralleled by increases in factor VIII in patients with ACLD/portal hypertension without active bacterial infection." (PMID 33000389, 2020). "We would also suggest cautious evaluation of CRP in HCC patients, the majority of whom are cirrhotic and could possibly have relatively lower baseline CRP values attributed to the severity of the underlying liver disease, leading to false negative results." (PMID 40948746, 2025). "Again, we show that when comparing patients without and with liver disease (CFLD), we could see that reduction of CRP was less marked in the latter group, suggesting that, in subjects with liver disease, the inflammatory status could take longer to be reduced." (PMID 36498475, 2022).
ulcerative colitis (166 papers, 2010 to 2026). An inflammatory bowel disease involving the mucosal surface of the large intestine and rectum. "An ulcerative colitis mouse model was established by subjecting CRP-deficient mice to dextran sulfate sodium (DSS) treatment." (PMID 39380742, 2024). "Other studies showed that low serum albumin and high CRP levels are associated with severe disease activity in patients with ulcerative colitis." (PMID 35011900, 2021). "For ulcerative colitis, an increase in ferritin was associated with lower risk, even after adjustment for CRP." (PMID 32541236, 2020). "In another study, the association between the CRP/albumin ratio and therapy responsiveness was assessed among patients with severe acute ulcerative colitis." (PMID 33193910, 2020). "In addition, C-reactive protein (CRP), fecal calprotectin, and fecal ferritin also have certain significance for the diagnosis of ulcerative colitis, but they are susceptible." (PMID 36445533, 2023). "However, we found positive associations of levels of TfGP14 and ulcerative colitis, and levels of TfGP28 and C-reactive protein levels, LDL and total cholesterol, although these results relied on few instrumental variables and were driven by associations in a single locus." (PMID 35332118, 2022). "Disease activity was assessed using the Pediatric Ulcerative Colitis Activity Index, and laboratory markers including C-reactive protein and erythrocyte sedimentation rate were measured." (PMID 42081144, 2026). "The results showed that serum C‐reactive protein (CRP) levels and clinical symptoms in patients with ulcerative colitis were decreased significantly in the fiber‐enriched and fiber‐reinforced group." (PMID 40432400, 2025). "We found that patients with familial ulcerative colitis had a greater clinical response, remission, and normalisation of CRP after one year, with p-values of 0.018, 0.002, 0.002, and 0.003, respectively, compared to patients with sporadic ulcerative colitis." (PMID 41398905, 2025). "In the context of ulcerative colitis, its main role is as a pro-inflammatory messenger, stimulating acute-phase proteins such as C-reactive protein, serum amyloid A, fibrinogen, and hepcidin from hepatocytes." (PMID 41356879, 2025). "Patients with CD showed significantly higher mean levels of ESR, CRP, and platelet count compared to their mean levels in patients with ulcerative colitis." (PMID 40519394, 2025). "M30, C-reactive protein, and mean platelet volume were evaluated in all participants and compared between ulcerative colitis patients and controls, as well as between those with active disease or remission." (PMID 39292076, 2024). "Baseline hemoglobin (g/dL), C-reactive protein (CRP) (mg/L), albumin (gm/dL), and ulcerative colitis endoscopic index of severity (UCEIS) were 11±1.18, 121.2±76.8, 2.32±0.49, and 4.75±0.5, respectively." (PMID 39544600, 2024). "Regarding the FC and CRP values in patients with Ulcerative Colitis, during the treatment with originator Adalimumab, three patients had FC values > 200 μg/g, three had FC values between 200 and 50 μg/g, and five had FC values < 50 μg/g." (PMID 39458960, 2024). "LCN2 serves as a dependable indicator of illness severity in ulcerative colitis and CD, differentiating between active disease and remission with heightened sensitivity compared to CRP." (PMID 38926732, 2024). "CRP levels also predict the likelihood of surgery in patients with both ulcerative colitis and Crohn’s disease." (PMID 39554800, 2023). "On the other hand, different CRP levels correlate with the clinical and endoscopic activity of ulcerative colitis." (PMID 36984554, 2023). "There was a significant statistical difference between all ulcerative colitis patients and the control group in both endocan level and CRP levels (p < 0.001)." (PMID 37041496, 2023).
ulcerative colitis (continued). "Our results exhibited significant increases in FC and CRP, IL-6, AOPPs, MTs, and p53Abs in ulcerative colitis patients with parasitic infections compared to those without parasites." (PMID 37710023, 2023). "According to a study that monitored patients with IBD, CRP levels were more specific for Crohn’s than for ulcerative colitis." (PMID 39554800, 2023). "There was a significant statistical difference between all patients with ulcerative colitis and the control group in both endocan level and CRP level (p < 0.001)." (PMID 37041496, 2023). "A similar study in ulcerative colitis using the modified Baron's index also found that FC correlated better with endoscopic disease activity than CRP (r=0.821 vs. 0.556)." (PMID 36873123, 2023). "CRP is a poor parameter of inflammation, especially in ulcerative colitis; about 50% of ulcerative colitis patients have normal CRP during a disease flare." (PMID 37761298, 2023). "In another RCT (n 90), ulcerative colitis patients received a 300,000 IU D3 injection which after 90 days resulted in a significant drop in CRP concentrations." (PMID 37379302, 2023). "Multiple studies included in this study showed that vitamin D supplementation effectively reduced the levels of inflammatory factors (IL-6, TNF-α, and CRP) in patients with ulcerative colitis." (PMID 35912148, 2022). "The mean CRP levels were 22 mg/dl in ulcerative colitis patients with active disease and 1.1 mg/dl in remission patients (p < 0.001)." (PMID 35140782, 2022). "Prostaglandin E-major urinary metabolite (PGE-MUM) and C-reactive protein (CRP) are useful biomarkers in patients with ulcerative colitis." (PMID 34376764, 2021). "Machine learning model optimized only on CRP level provides a very poor prediction for ulcerative colitis, which is expressed in low average precision of 67%, and positively found true cases of disease incidence, with recall metric of only 34%." (PMID 34682868, 2021). "A similar result for the predictive capacity of CRP at week 2 has been previously reported in ulcerative colitis patients." (PMID 34567565, 2021). "We evaluated the association between endoscopic scores of colonic inflammation and fecal calprotectin (FC), fecal immunochemical occult blood test (FIT), and C-reactive protein (CRP) in patients with ulcerative colitis (UC)." (PMID 34127687, 2021). "A total of 199 colonoscopic examinations were conducted in 108 ulcerative colitis patients who underwent C-reactive protein and serum amyloid A blood tests." (PMID 32245401, 2020). "The aim of the study was to evaluate serum FGF19 level and its correlation with clinical and endoscopic disease activity indices along with inflammatory biomarkers including serum CRP and fecal calprotectin levels in patients with ulcerative colitis (UC)." (PMID 32565779, 2020). "Serum amyloid A is a more useful marker compared to C-reactive protein in predicting mucosal inflammation in ulcerative colitis patients in clinical remission." (PMID 32245401, 2020). "Patients with ulcerative colitis showed a decrease in serum C-reactive protein (CRP) levels when given a fiber-based prebiotic, as well as a reduction in abdominal pain and cramping." (PMID 33520902, 2020). "This excessive circulating PB response corresponds to flaring of the underlying inflammatory disease, and specifically correlates with c-reactive protein (CRP) level in studies on ulcerative colitis and IGG4 related disease." (PMID 31013925, 2019). "A high IL-10 serum level is maintained during the early phase of remission in some human ulcerative colitis patients, whereas C-reactive protein and IL-6 serum levels return to normal during remission after an increase during the acute phase." (PMID 31244763, 2019). "Despite even severe, extensive, active ulcerative colitis, the circulating CRP concentration was generally modestly increased if at all." (PMID 30459761, 2018).